LEP (leptin)
Diseases named in the same sentence as LEP in open-access papers (continued):
Sharing a sentence is not in itself a finding about the gene and the disease.
Obesity (continued). "Therefore, the hyper-methylation of SOCS3 in the gene promoter and its nearby region silences the inhibitory effect on leptin and insulin of SOCS3, whereas hyper-methylation in the gene body facilitates it to inhibit the activity of insulin and leptin, resulting in a high risk of obesity." (PMID 36145200, 2022). "It remains unclear, however, whether these changes in gut microbiome composition are due to the altered leptin action resulting from hyperphagia, from physiological changes associated with obesity, or from other leptin actions independent of food intake and adiposity." (PMID 35563103, 2022). "Various local or systemic cytokines are increased in obesity, including IL-1α, TNF-α, leptin, and IL-6, while IL-1α, in combination with TNF-α and IL-6, is involved in the pathology of atherosclerosis in obese individuals." (PMID 36311488, 2022). "Four target areas (leptin, ghrelin, mitochondrial uncouplers and growth differentiation factor 15 (GDF15)) were initiated and advanced with obesity constituting the primary therapeutic purpose." (PMID 34815532, 2022). "With high-fat diet (HFD) and knockout leptin gene mice (ob/ob), we found that ASC expression in subcutaneous adipose tissue (SAT) correlated with obesity." (PMID 36077447, 2022). "In conclusion, our study in a large population with obesity established that TSH levels show an upward trend with increasing degree of obesity in females and leptin levels emerged as the main metabolic determinant of thyroid function parameters in obesity." (PMID 36313780, 2022). "This may be attributed to the cytotoxicity of STZ that leads to rapid β-cell failure or elevated levels of leptin and adiponectin in diabetic rats, which mimics the pathophysiology of lean diabetes patients with severe insulin secretion defects compared with individuals with obesity." (PMID 36613966, 2022). "To date, the administration of recombinant human leptin and the MC4R agonist setmelanotide are two genotype-informed therapies for rare monogenic obesity." (PMID 35574020, 2022). "Adipocytokines, such as adiponectin, leptin, and IGF-1 are key regulators of energy metabolism and fat stores that are centrally involved in the pathomechanistic sequaele of adipositas and obesity." (PMID 34319428, 2022). "Topological analysis and modular analysis revealed the role of HJJPD in the treatment of simple obesity by acting on SOCS-3, JAK2, LepRB, LEP, IL-6, and STAT3 and influencing the JAK2-STAT3 pathway." (PMID 35529938, 2022). "In the attempt to identify obesity-driven tumour susceptibility pathways that might alter energy balance, leptin–LEPR signalling has been a focus of cancers of which the normal stem cells express LEPR and exist in a fatty tissue microenvironment in which local leptin is high." (PMID 36450983, 2022). "Similarly, GDF15 transgenic mice fed a HFD show reduced NLRP3 inflammasome activity and pro-inflammatory macrophage infiltration into white AT as well as lower serum leptin and insulin levels, suggesting that GFD15 could reduce obesity-associated inflammation and improve insulin sensitivity." (PMID 35909571, 2022). "Human research on leptin and ventilation is mainly carried out in patients with OSA or obesity and low-ventilation syndrome." (PMID 35162313, 2022). "Using a combination of methods of pharmacology and various mouse models of obesity, here we explore the role of SFN as a molecule at the intersection of the NRF2 pathway and central leptin signaling." (PMID 35323110, 2022). "Chitosan supplementation can improve cardiometabolic parameters (anthropometric indicators of obesity and lipid and glycemic markers) and appetite-related hormones (adiponectin, leptin, and NPY) in adolescents with overweight or obesity." (PMID 36064382, 2022).
Obesity (continued). "In the TME, adipokines secreted by the adipose tissue (e.g., leptin) impinge on the increase of VEGF and sustain neovascularization, further strengthening the importance of angiogenesis in the relationship between obesity and HCC development." (PMID 36074318, 2022). "In addition, it cannot be excluded that nutritional deficiencies may decrease leptin signaling leading to a lack of satiety, hyperphagia, obesity, inflammation, and in some cases TC." (PMID 35162142, 2022). "Accordingly, obesity is characterized by increased levels of circulating factors including insulin, insulin-like growth factor 1 (IGF-1), leptin, and inflammatory cytokines such as IL6 and TNFα." (PMID 36010901, 2022). "The present review explored the molecular and physiological adaptations of leptin, insulin, POMC, and AgRP neuropeptides to IF protocols, mostly performed in animal obesity models." (PMID 35445066, 2022). "A reduction in levels of obesity seems to produce a reduction on TNF-α, which lead to a decline in leptin and an increase in adiponectin and insulin sensitivity." (PMID 35529460, 2022). "Taken together, many animal studies furnish the role of leptin, adiponectin, and NPY in appetite modulation and systematic effects on obesity." (PMID 36064382, 2022). "However, it remains unclear whether compositional changes in the gut microbiota are due to hyperphagia or physiologic changes associated with obesity or from other leptin actions independent of food intake and adiposity." (PMID 36153588, 2022). "Early-pubertal girls with obesity also had significantly higher values (p < 0.05) for BMI-SDS, leptin, IGF-1, IGFBP3, insulin and HOMA-IR, LH, ratio LH/FSH, ACTH, DHE-S, androstenedione, testosterone and free testosterone levels than control group." (PMID 35412268, 2022). "Although leptin may be considered as a proinflammatory cytokine, the role of leptin has been largely explored in pathological conditions, such as metabolic syndrome and obesity, where there is an increase in proinflammatory interleukins related to leptin resistance." (PMID 35884769, 2022). "In humans, studies have shown that MUHO sufferers have higher leptin resistance than MHO sufferers, supporting the idea that leptin is a key part of the obesogenic progression to unhealthy obesity." (PMID 36143948, 2022). "We demonstrate here that maternal obesity leads to early-onset obesity with WAT overactivity and elevated serum IL-6 and leptin concentrations in the offspring." (PMID 35896539, 2022). "Previous studies show positive correlations between Leptin, Visfatin, Resistin and Adipsin and circulating inflammatory markers such as IL-6 and CRP in individuals suffering from obesity." (PMID 35684160, 2022). "In both genders, CNTF levels correlated significantly and positively with obesity (BMI, WHR, leptin), diabetes (fasting insulin, HOMA index and HbA1c) and inflammation (IL-6 and hsCRP) indices." (PMID 35585213, 2022). "Interestingly, in humans with obesity, the positive relationship between plasma leptin and sucrose recognition thresholds disappears and is replaced by a negative one such that higher leptin levels are associated with increased sucrose sensitivity; this outcome was attributed to leptin resistance." (PMID 35215527, 2022). "Moreover, numerous studies have demonstrated that oxidative stress and inflammation contribute to the progress of obesity by inducing skeletal muscle dysfunction and reducing energy expenditure, as well as by inducing the resistance of leptin and insulin which could govern energy homeostasis." (PMID 36466427, 2022). "In fact, an attenuated fall in postprandial ghrelin levels, leptin resistance, lower levels of peptide tyrosine-tyrosine (PYY), and glucagon-like peptide 1 (GLP-1) are usually present in obesity, as reviewed by Miller, Ullrey and Perry, Wang." (PMID 34928408, 2022).
Obesity (continued). "A number of research works have attributed the gut microbiota to obesity, owing to the direct modulating action of GBA on the appetite‐related hormones, i.e., leptin (LEP), ghrelin, and glucagon‐like peptide 1 (GLP‐1)." (PMID 35421277, 2022). "In obesity, WAT expansion leads to a significant decrease of serum adiponectin levels and an increase in leptin levels that are correlated with insulin resistance." (PMID 36297569, 2022). "Leptin levels were widely investigated in OSA and found to be increased even after adjustment for obesity." (PMID 36359273, 2022). "Furthermore, although obesity and infertility are seen in leptin‐deficient ob/ob mice, these phenotypes are ameliorated in NPY‐deficient ob/ob mice, suggesting that NPY functions as a central effector that mediates the effects of leptin on the appetite and reproductive systems." (PMID 34934398, 2022). "Furthermore, leptin was shown to drive the obesity-dependent changes in global DNA methylation and gene expression in the adipose tissue of diet-induced or genetically obese mice, with evidence for obesity related global DNA hypomethylation and subsequent increased gene expression." (PMID 36855701, 2022). "Prepubertal girls with obesity had significantly higher values (p < 0.05) for BMI-SDS, leptin, insulin and HOMA-IR levels than control group." (PMID 35412268, 2022). "Additionally, leptin and other adipocytokines can jointly induce the recruitment and activation of immune cells during WAT expansion in obese mice, create a pro-inflammatory environment and promote the release of free fatty acids, so as to exacerbate obesity-associated metabolic inflammation." (PMID 35281054, 2022). "However, leptin’s stimulatory effect on fatty acid oxidation is absent in obese people, and leptin resistance is one of the causal factors of cardiovascular complications in obesity." (PMID 35967818, 2022). "There are two hypotheses about the relationship between obesity and asthma: one is diaphragm excursion due to fat deposit and limited thoracic compliance, and one is the immunological and inflammatory adipokines derived from adipose tissue, such as leptin and adiponectin." (PMID 36551211, 2022). "It was suggested that obesity and the diagnosis of PCOS itself affect the serum leptin level almost equally." (PMID 36246904, 2022). "Our results indicate that SFN confers protection against diet-induced obesity in an NRF2 and leptin-dependent manner." (PMID 35323110, 2022). "It participants the metabolism of arachidonic acid by catalyzing oxaloacetic acid (OAA) to produce prostaglandin E2 (PGE2), which stimulates the production of leptin through EP3, thus promoting adipogenesis and inhibiting lipolysis to promote obesity." (PMID 35237299, 2022). "Patients with severe obesity who completed a milk-based LELD had significant short-term increases in adiponectin and reductions in leptin and the LAR, consistent with decreased insulin resistance, which was proportional to the amount of weight lost." (PMID 35662920, 2022). "Children with obesity have more receptors for growth hormone (GH), higher levels of insulin-like growth factor-1 (IGF-1), and higher levels of leptin and insulin." (PMID 36554686, 2022). "Furthermore, insufficient sleep duration may decrease levels of melatonin and leptin as well as elevate levels of ghrelin and cortisol, which may further result in obesity, diabetes, hyperinsulinemia, dyslipidemia, and hypertension, thereby aggravating the burden on the kidney." (PMID 36504942, 2022). "To investigate if leptin might play a role in influencing the severe disease symptoms in obese COVID-19 patients, we determined whether endothelial cells were susceptible to SARS-CoV-2 infection and whether mediators of obesity such as leptin would promote endothelial activation in vitro." (PMID 35837388, 2022).
Obesity (continued). "The obesity- and inflammation-related gene (IL-6, TNF-α, IGF-1, leptin, AP2/FABP4, AMPK-α2, β3AR, and PPAR-γ) expressions in the liver and epididymal adipose tissue were reduced in the PHPB-treated group." (PMID 35386305, 2022). "New interventions targeting LEP, NOTCH1, SPRY1, PPARG, ID2, and CIDEA gene network, in addition to what already is going on, can be designed for treatment and prevention of both obesity and tumors." (PMID 35395810, 2022). "Further knowledge of the role of leptin in adipose tissue, mechanisms and pathways involved, and its regulation may be of interest in the design of new strategies for the prevention and treatment of obesity and related pathologies, even from early stages of life." (PMID 34523036, 2022). "We have shown that in a cohort of adults with severe obesity who completed a 24-week milk-based LELD, there were substantial increases in adiponectin and reductions in leptin and LAR, consistent with increased insulin sensitivity." (PMID 35662920, 2022). "Adipocyte enhancer-binding protein 1 (AEBP1) rises in obesity, causing a drop in PTEN activity and consequent stimulation of adipocyte proliferation in mice and this increase in adipocyte proliferation may lead to further crosstalk between adipocytes and tumour cells, for instance by leptin." (PMID 36038791, 2022). "Partial leptin reduction improved leptin and insulin sensitivity and decreased body weight in mice with HFD-induced obesity." (PMID 36012616, 2022). "At the limits, this is exemplified by the ob/ob and db/db mice that lack leptin and the long form of the LEPR, respectively, and have elevated food intake, suppressed metabolism, and enormous obesity." (PMID 36394061, 2022). "Leptin (LEP) and Follistatin-related protein 3 (FLSTL3) were significantly higher in the MOD cluster and of course increased leptin levels in obesity reflects resistance to leptin action." (PMID 36402758, 2022). "Therefore, it is assumed that PG may improve leptin resistance‐induced obesity." (PMID 35154693, 2022). "Ablation of GIP in Lepob/ob mice, did not prevent body weight gain and insulin resistance, suggesting that endogenous GIP may not have a role in the development of obesity in leptin deficient mice, indicating that the crosstalk between leptin and GIP secretion warrants further investigation." (PMID 35409202, 2022). "Moreover, correlations between these metabolic dysfunctions and the adiponectin/leptin serum ratio appear to be stronger than those observed with adiponectin or leptin serum levels alone, likely because both adipokines are involved in the low-grade systemic inflammation present in obesity." (PMID 35806353, 2022). "In the reverse MR analysis, we also observed effects of BMI (both childhood and adult) on obesity-related biomarkers, such as CRP, IGF1, insulin, leptin, and TNFR2." (PMID 36253437, 2022). "For example, leptin, progranulin, chemerin, and MCP-1 act as chemokines for immune cell (macrophages and DCs) infiltration into AT during obesity." (PMID 35909571, 2022). "A total of 524 blood samples from children with obesity (age 10–16 years old) were analyzed for FBG, lipids, insulin, leptin, and adiponectin." (PMID 35370951, 2022). "Leptin promotes breast cancer development by stimulating breast epithelial cell stemness and drives BCSC enrichment to promote tumorigenesis in an obesity-driven TNBC model." (PMID 35805056, 2022). "Both oxytocin and leptin impact the neurodevelopment during critical periods and are affected by ELS and obesity." (PMID 35203274, 2022). "Importantly, celastrol does not have any effect in leptin-deficient db/db or ob/ob mice, the observations validating celastrol as a leptin sensitiser, which provides evidence that celastrol holds potential in treating leptin-resistant obesity." (PMID 36009315, 2022). "Mechanistically, ACC1 is phosphorylated and inactivated by leptin or transforming growth factor-β (TGF-β) signaling, which is highly expressed in obesity." (PMID 36577755, 2022).
Obesity (continued). "According to the literature, several factors influence changes in the body weight of D. melanogaster fed obesity diets, including age, mating, insulin/IGF signaling pathway modulation and leptin expression in the brain." (PMID 35204807, 2022). "In this context, obesity-related inflammation may contribute to leptin resistance, which in turn further increases weight gain and leptin levels, which then increases the inflammation-related obesity, since leptin is an important proinflammatory adipokine, activating monocytes and lymphocytes." (PMID 35563589, 2022). "In obesity, SOCS1/3 are induced by the chronically increased signaling of pro-inflammatory cytokines, including leptin, via the JAK/STAT pathway." (PMID 35406000, 2022). "In patients with extreme obesity, elevated TSH concentration significantly correlated with proinflammatory cytokines such leptin, IL6, ICAM-1 and E-selectin." (PMID 34574358, 2021). "Despite the remarkable results of leptin-based therapy on weight loss in genetically predisposed obese subjects (mutations in the leptin gene), this approach has a limited or completely absent effect on weight loss in subjects with common obesity, especially in hyperleptinemic patients." (PMID 34084149, 2021). "Neuron-specific deletion of the SHP2 results in obesity and leptin resistance in mice, suggesting that the SHP2 pathway is also important in mediating leptin’s anti-obesity action." (PMID 33849593, 2021). "It is known that leptin level is elevated in obesity and T2DM, and resistance to leptin action is widely accepted." (PMID 33672162, 2021). "We showed the link between leptin signaling and NLRP3 inflammasome activation in the ovary throughout obesity progression in mice, elucidating the molecular mechanisms underpinning ovarian failure in maternal obesity." (PMID 34805147, 2021). "Excitingly, they found that this impaired leptin responsiveness could be reversed in obese mice by pre-treating orally with a chemical chaperone to enhance ER function; thus giving rise to a novel class of leptin-sensitising, anti-obesity drugs targeting ER stress." (PMID 34613819, 2021). "More recent arguments implicate leptin, an anorectic hormone, and the leptin resistance in hypopituitarism, in the pathogenesis of NAFLD, via insulin resistance, hyperphagia, and obesity." (PMID 33505943, 2021). "In the genetic Zucker rat obesity model, EA treatment at Zhongwan (RN12) and Guanyuan (RN4) acupoints led to significantly lower serum leptin and higher adiponectin/leptin ratio compared to an obese control group." (PMID 34630614, 2021). "Regulating insulin and leptin levels using a protein tyrosine phosphatase 1B (PTP1B) inhibitor is an attractive strategy to treat diabetes and obesity." (PMID 34299651, 2021). "In contrast to leptin, TGF-β1 can increase IL-6 mRNA expression and IL-6 protein release, as recently reported in the field of obesity and metabolic syndrome." (PMID 34327205, 2021). "We note that body fat percentage positively correlates with serum leptin in IIH patients (P < 0.0001, r = 0.74) as it does in obesity." (PMID 33848268, 2021). "Despite the lack of tissue specificity in hypothalamic SOCS3 knockdown-mediated protection against diet-induced obesity, collectively these studies firmly implicate SOCS3 as a molecular mediator of ARC leptin resistance." (PMID 34613819, 2021). "The obesity-related low-grade chronic inflammation is generated by the production of pro-inflammatory cytokines, as IL-6 and TNF-α, and adipokines, as leptin." (PMID 33498674, 2021). "PTP1B is elevated in obesity, and both whole body and brain-specific PTP1B knockout mice exhibit improved leptin sensitivity and partial resistance to diet-induced obesity." (PMID 34502119, 2021). "According to the current findings, it is known that the pivotal targets of acupuncture for improving obesity are mainly focused on the neurons or neuropeptides in the hypothalamic ARC, the peripheral hormones (leptin and insulin)." (PMID 33868169, 2021).